PHGDH (phosphoglycerate dehydrogenase)
Diseases named in the same sentence as PHGDH in open-access papers (continued):
Sharing a sentence is not in itself a finding about the gene and the disease.
osteosarcoma (continued). "Similarly, MYC-PHGDH ablation restores radiosensitivity in GSCs, while PHGDH inhibitors combined with mTORC1 blockade induce osteosarcoma apoptosis." (PMID 41486146, 2026). "Osteosarcoma is a bone cancer that has been found to be metabolically dependent on the conversion of glucose to serine through the rate-limiting enzyme 3-phosphoglycerate dehydrogenase (PHGDH)." (PMID 39934141, 2025). "Next, the knockdown of PHGDH or inhibition of PHGDH activity could eliminate the effect of RFWD3 knockdown on NAD+ and serine level, indicating that RFWD3 modulated osteosarcoma cell metabolism via PHGDH." (PMID 40019400, 2025). "Subsequently, we aimed to elucidate the role of PHGDH in DDP resistance in osteosarcoma." (PMID 40019400, 2025). "Furthermore, in vivo experiments confirmed that PHGDH overexpression enhanced the sensitivity of osteosarcoma to DDP treatment." (PMID 40019400, 2025). "The results showed that the effect of RFWD3 knockout on DDP sensitivity could be partially mitigated by a low dose of the PHGDH inhibitor NCT‐503, indicating that PHGDH partially mediated the RFWD3‐induced DDP resistance in osteosarcoma." (PMID 40019400, 2025). "PHGDH inhibition in osteosarcoma cell lines attenuated cellular proliferation without causing cell death, prompting a robust metabolic analysis to characterize pro-survival compensation." (PMID 33503424, 2021). "Additionally, DDP treatment significantly elevated the ubiquitination levels of PHGDH, indicating that PHGDH ubiquitination by RFWD3 may play a crucial role in osteosarcoma cells’ response to DDP treatment." (PMID 40019400, 2025). "RNA-seq data from the Cancer Cell Line Encyclopedia (CCLE; Broad Institute) indicated relatively low-baseline mRNA expression of the serine transporter ASCT2/SLC1A5, which could explain why PHGDH inhibition cannot be compensated for with extracellular serine and glycine in osteosarcoma cells." (PMID 33503424, 2021). "Therefore, the possibility that PHGDH inhibition could sensitize osteosarcoma cell lines to cell death by an mTORC1 inhibitor was explored." (PMID 33503424, 2021). "Given the critical role of PHGDH as a metabolic enzyme, we proceeded to investigate the influence of RFWD3 on the metabolic pathways in osteosarcoma cells." (PMID 40019400, 2025). "The downregulation of PHGDH conserves NAD+, thereby enhancing the TCA cycle and promoting de novo nucleotide biosynthesis, which in turn supports DNA repair and contributes to DDP resistance in osteosarcoma." (PMID 40019400, 2025). "Given the significantly shorter overall survival in patients with high PHGDH expression, there is likely a large subset of patients with osteosarcoma that do not benefit from exposure to high-dose methotrexate." (PMID 33503424, 2021). "This suggests that osteosarcoma cell lines with high levels of PHGDH likely are not dependent on extracellular serine." (PMID 33503424, 2021). "Non-rapalog mTORC1 inhibition combined with PHGDH inhibition demonstrates a possible synergistic dual metabolic therapy for osteosarcoma." (PMID 33503424, 2021). "Importantly, because PHGDH inhibition does result in decreased cell proliferation, de novo serine biosynthesis does provide some of the nutrients required for biomass production and proliferation but does not encompass the entire survival capacity of osteosarcoma." (PMID 33503424, 2021).
prostate carcinoma (7 papers, 2016 to 2025). A carcinoma that arises from epithelial cells of the prostate gland. "To confirm that PLK1 OE leads to the decrease of PHGDH in prostate cancer, we overexpressed PLK1 in LNCaP, C4–2 and 22Rv1 cells, and found that PLK1 OE leads to the decrease of PHGDH." (PMID 40475404, 2025). "We further confirmed the downregulation of SSP in advanced prostate cancer cell lines and advanced prostate cancer patient-derived xenografts (PDXs), which show the downregulation of PHGDH, the first and rate-limiting enzyme of SSP." (PMID 40475404, 2025). "Androgen deprivation, an effective therapy for the early-stage prostate cancer, led to an increase in PHGDH in LNCaP cells (Fig. EV3D)." (PMID 40475404, 2025). "To examine further the characteristics of PHGDH expression, we created limiting dilutions of two of the cell lines, the DU-145 and PC-3 prostate cancer-derived cell lines." (PMID 29925909, 2018). "Similarly, elevated phosphoglycerate dehydrogenase (PHGDH) levels contribute to resistance in castration-resistant prostate cancer patients against the androgen receptor inhibitor enzalutamide." (PMID 38844964, 2024). "Notably, recent research has shown that PHGDH can regulate ferroptosis, thereby influencing enzalutamide resistance in prostate cancer and malignant progression in bladder cancer." (PMID 39223162, 2024). "Our finding that PLK1 leads to the decrease of PHGDH, thus decreasing of SSP in prostate cancer, which is reminiscent of checking inosine monophosphate (IMP), the downstream purine from glucose and one carbon metabolism." (PMID 40475404, 2025). "To determine if knocking down (KD) PLK1 in advanced prostate cancer cells, such as DU145, leads to the upregulation of PHGDH, we knocked down PLK1 in both C4–2 and DU145 cells, and observed an increase in PHGDH." (PMID 40475404, 2025). "The combination treatment of PHGDH inhibitor NCT-503 and PLK1 inhibitor Onvansertib effectively block the prostate cancer growth." (PMID 40475404, 2025). "The downregulation of PHGDH, a key enzyme often upregulated in other cancer types and non-catalytically expressed lower in cancer dissemination and metastasis, underscores PLK1’s unique ability to redirect metabolic flux in prostate cancer." (PMID 40475404, 2025). "Our unbiased lipidomic screening found out the enhanced sphingolipid synthesis by PLK1 in prostate cancer cell line LNCaP, and we confirmed the significant incorporation of exogenous serine into ceramide, which accounts for over 1% of detected sphingolipids (Table EV4) in C4–2 PHGDH mutant cells." (PMID 40475404, 2025).
Alzheimer disease (6 papers, 2016 to 2026). A progressive, neurodegenerative disease characterized by loss of function and death of nerve cells in several areas of the brain leading to loss of cognitive function such as memory and language. "The therapeutic implications of these findings are profound, paving the way for novel diagnostic tools, such as PET probes for assessing PHGDH compartmentalization, and promoting a synergistic approach to "exercise-pharmacotherapy" in the treatment of Alzheimer's disease." (PMID 41893345, 2026). "Phosphoglycerate dehydrogenase (PHGDH) is a key molecule in the progression of Alzheimer's disease." (PMID 41344159, 2025).
bladder cancer (6 papers, 2020 to 2024). "Other tumors: In bladder cancer (BCa), an important serine metabolism enzyme, phosphoglycerate dehydrogenase (PHGDH), is highly expressed." (PMID 38072908, 2023). "The expression level of PHGDH was correlated with the clinicopathological features of bladder cancer, and the prognosis of patients with high PHGDH expression was poor." (PMID 35629893, 2022). "This research investigated PHGDH, a key enzyme in the serine biosynthesis, in bladder cancer." (PMID 32386122, 2020). "Therefore, we further explored whether circSIRT5 regulates ferroptosis mediated by PHGDH in bladder cancer to exert its anticancer effects." (PMID 39223162, 2024). "There have been no investigations of the role of PHGDH expression in bladder cancer (BC)." (PMID 32386122, 2020).
cervical cancer (6 papers, 2014 to 2023). A primary or metastatic malignant neoplasm involving the cervix. "In addition, high PHGDH expression in cervical cancer was associated with large tumor size, high FIGO stage, and aggressiveness." (PMID 36803157, 2023). "However, unlike phosphoglycerate dehydrogenase, PLR is a cheap and easily available biomarker that may be an independent predictor of poor prognosis in patients with cervical cancer." (PMID 26885692, 2016).
diabetes (6 papers, 2017 to 2025). "PHGDH's critical function in adipose tissue glucose metabolism positions it as a therapeutic target for diabetes with our study revealing an unexplored link to COPD." (PMID 40045538, 2025). "Specifically, IRS1 and PHGDH emerge as the DE RNAs causative of nutritional and metabolic associated diseases, as they are extremely relevant and characterized in diabetes, lipidemia, obesity (IRS1), and phosphoglycerate dehydrogenase deficiency (PHGDH)." (PMID 33924951, 2021). "The inverse association between DNA methylation and UACR was stronger in those with diabetes (cg14476101 in PHGDH, cg19693031 in TXNIP, and cg06690548 in SLC7A11) or those who were obese (cg06690548 in SLC7A11)." (PMID 32917208, 2020). "Specifically, IRS1 and PHGDH emerge as the DE RNAs causative of nutritional and metabolic associated diseases, and these are two regulators extremely relevant and characterized in diabetes, lipidemia, obesity (IRS1), and phosphoglycerate dehydrogenase deficiency (PHGDH)." (PMID 33924951, 2021). "The regulation of diabetes is caused by genes including ASNS, CAD, GMPS, and PHGDH." (PMID 33490239, 2020).
fatty liver disease (6 papers, 2020 to 2025). A reversible condition wherein large vacuoles of triglyceride fat accumulate in liver cells via the process of steatosis. "Among them, cg14476101 is significantly associated with expression of the PHGDH and risk of fatty liver disease." (PMID 33990564, 2021). "The CpG cg14476101 and its annotated gene (PHGDH) have been reported in previous studies to be associated with fatty liver disease and adiposity." (PMID 33990564, 2021). "In liver macrophages, PHGDH suppresses the activation of NF-κB and MAPK signaling to alleviate metabolic dysfunction-associated fatty liver disease." (PMID 40598535, 2025). "In fact, decreased hepatic levels of serine, due to a downregulation of phosphoglycerate dehydrogenase, contribute to the development of fatty liver disease." (PMID 36060961, 2022). "To gain further insight into the biological mechanism linking PHGDH to fatty liver disease, we conducted experimental studies." (PMID 33990564, 2021). "Interestingly, 3-phosphoglycerate dehydrogenase (PHGDH), the key enzyme involved in the de novo synthesis of serine, is also closely associated with the development of fatty liver diseases." (PMID 34712382, 2021).
Neu-Laxova syndrome (6 papers, 2020 to 2026). Neu-Laxova syndrome (NLS) is a rare, multiple malformation syndrome characterized by severe intrauterine growth retardation (IUGR), severe microcephaly with a sloping forehead, severe ichthyosis (collodion baby type), and facial dysmorphism. "Human pathophysiological evidence comes from biallelic PHGDH loss-of-function mutations causing lethal Neu-Laxova syndrome, a neurodevelopmental disorder characterized by severe neurological deficits." (PMID 41486146, 2026). "Neu-Laxova syndrome is an autosomal recessive disorder caused by mutations to PHGDH and subsequent loss of serine, and is characterized by neurological impairment, impaired fetal development, and skeletal anomalies." (PMID 33511334, 2020). "Later studies found that phenotypes of PHGDH deficiency can exist on a spectrum and identified Neu-Laxova syndrome as a more severe example of PHGDH deficiency." (PMID 33511334, 2020). "The therapeutic promise of PHGDH inhibition is tempered by neurotoxicity risks stemming from central serine depletion, recapitulating neurological deficits observed in Neu-Laxova syndrome." (PMID 41486146, 2026). "The PHGDH is also responsible for the development of neurological genetic Neu-Laxova Syndrome." (PMID 33924951, 2021). "Genetic deficiency in the de novo serine biosynthesis genes PHGDH, PSAT1, and PSPH, in humans causes Neu-Laxova syndrome (NLS), a very rare autosomal recessive congenital disorder." (PMID 32549981, 2020).
sarcoma (6 papers, 1988 to 2025). A usually aggressive malignant neoplasm of the soft tissue or bone. "Some ASS1-deficient sarcomas reportedly exhibit compensatory upregulated serine synthesis and increased sensitivity to PHGDH inhibitors in response to arginine depletion." (PMID 36319669, 2022). "Much like the results from the rat sarcoma, the activity of PHGDH was found to be elevated 10-fold, and that of serine hydroxymethyltransferase nearly 5-fold, in tumors relative to healthy colon mucosa." (PMID 25574168, 2014). "In addition to the expression level, the enzyme activity of PHGDH in rectal cancer cells and sarcoma models also increased significantly, and it has become a new target for cancer treatment and drug discovery at present." (PMID 35008393, 2022). "We also knockdown PLK1 and overexpressed the constitutively active PLK1 T210D (TD) in sarcoma cell line U2OS, and found PHGDH increased upon PLK1 KD, while PHGDH decreased upon TD overexpression." (PMID 40475404, 2025). "However, in our screen, silencing of PSAT1, PHGDH or BCAT1 did not inhibit sarcoma cell growth, suggesting that these biosynthetic pathways may be of lesser importance for the sarcomatous malignancies studied here." (PMID 26499495, 2015).
Burkitt lymphoma (5 papers, 2020 to 2024). A rare form of malignant mature B-cell non-Hodgkin lymphoma. "In Burkitt’s lymphoma, PHGDH and PSAT1 are upregulated by the action of MYC/ATF4, therefore, increasing the activity of the glycine–serine pathway." (PMID 34968247, 2021). "In Burkitt’s lymphoma, chemical inhibition of PHGDH resulted in decreased DNA and histone methylation, reactivation of tumour suppressor genes, and decreased proliferation." (PMID 34968247, 2021). "Burkitt lymphomas, highly proliferative and metabolically demanding tumors, overexpress serine biosynthesis pathway (SBP) enzymes, phosphoglycerate dehydrogenase (PHGDH), and phosphoserine aminotransferase 1 (PSAT1)." (PMID 32138178, 2020).
endometrial cancer (5 papers, 2022 to 2024). Primary or metastatic malignant neoplasm involving the endometrium (mucous membrane that lines the endometrial cavity). "Multifactorial COX regression analysis further supported that high PHGDH expression was an independent risk factor associated with prognosis in patients with endometrial cancer." (PMID 36803157, 2023). "At the same time, Cytokine-cytokine receptor interaction (hsa04060) and Staphylococcus aureus infection (hsa05150) were also associated with the role of PHGDH in endometrial cancer." (PMID 36803157, 2023). "PHGDH is associated with immune response and immune infiltration in endometrial cancer, especially in CD8+ T cells." (PMID 36803157, 2023). "Multifactorial COX analysis indicated that high expression of PHGDH could be an independent risk factor for PFI in endometrial cancer patients." (PMID 36803157, 2023). "PHGDH plays a vital role in the development of endometrial cancer, which is related to tumor immune infiltration, and can be used as an independent diagnostic and prognostic marker for endometrial cancer." (PMID 36803157, 2023). "The independent diagnostic value of PHGDH expression in endometrial carcinoma." (PMID 36803157, 2023). "This inhibition of PHGDH expression not only reduced the proliferation of endometrial cancer cells but also induced apoptosis, leading to a decrease in the metastasis of these cancer cells." (PMID 38945960, 2024). "In endometrial cancer, the knockdown of PHGDH was found to significantly inhibit the migration of cancer cells in vitro." (PMID 38945960, 2024). "The GO pathways related to the position of PHGDH in endometrial cancer include receptor ligand activity (GO:0048018), external side of plasma membrane (GO:0009897), humoral immune response (GO:0006959), etc." (PMID 36803157, 2023). "The protein expression level of PHGDH was also significantly upregulated in endometrial cancer tissues compared to normal endometrial tissues, indicating that PHGDH protein and mRNA had similar expression profiles in different databases." (PMID 36803157, 2023). "The results showed that the expression level of PHGDH gene in primary endometrial cancer tissues was significantly higher than that in normal endometrial tissues (P < 0.001)." (PMID 36803157, 2023). "Our study was the first to analyze the relationship between the serine metabolism-related gene PHGDH and the development of endometrial cancer and to develop a nomogram model that included clinical features." (PMID 36803157, 2023). "The expression pattern of PHGDH gene in 552 cases of endometrial cancer tissues and 35 cases of normal endometrial tissues was predicted using the TCGA database." (PMID 36803157, 2023). "Our study showed for the first time that PHGDH expression was significantly upregulated at both mRNA and protein levels in endometrial cancer tissues compared to normal tissues." (PMID 36803157, 2023). "Subsequently, nomogram models predicting the survival of patients with endometrial cancer were constructed using age, clinical stage, histological grade, tumor invasion, histological type, and PHGDH levels." (PMID 36803157, 2023). "The relationship between PHGDH expression and clinical characteristics of endometrial cancer was investigated by logistic regression." (PMID 36803157, 2023). "In summary, the analysis showed that PHGDH expression was higher in endometrial cancer tissues than in normal endometrial tissues and correlated with the prognosis of patients." (PMID 36803157, 2023). "The effect of PHGDH expression on the prognosis of endometrial cancer was analyzed by Kaplan-Meier plotter and Cox regression." (PMID 36803157, 2023). "Next, we explored the relationship between PHGDH expression and clinicopathological features of endometrial cancer." (PMID 36803157, 2023). "This study aimed to determine the prognostic value of PHGDH in endometrial cancer using comprehensive bioinformatics analysis." (PMID 36803157, 2023).